CRP (C-reactive protein)
Diseases named in the same sentence as CRP in open-access papers (continued):
Sharing a sentence is not in itself a finding about the gene and the disease.
metabolic syndrome (continued). "In one study, patients suffering from the metabolic syndrome demonstrated wider QRS‐T angles, and a correlation between CRP levels and QRS‐T angles was observed." (PMID 32638456, 2020). "The presence of the A-allele has been correlated with inflammatory processes, higher C-reactive protein (CRP) levels, and development of metabolic syndrome, but in clinical observations this effect is very often lost due to multiple confounding factors." (PMID 31275366, 2019). "There are similar reports about higher levels of Hcy and CRP in MS and SLE patients with metabolic syndrome." (PMID 31130913, 2019). "The association between ADPN and FVC in % of predicted remained positive after adjusting for smoking status, weight, BMI, metabolic syndrome, OSA and CRP one by one in separate linear regression models." (PMID 29609563, 2018). "This dietary pattern was significantly correlated with increased CRP and NLR levels in the subjects with metabolic syndrome." (PMID 30454030, 2018). "Both CRP and NLR serve as inflammatory indicators that can be easily measured and serve as independent predictors for both the development of metabolic syndrome and CVD." (PMID 30454030, 2018). "Adipose tissue dysfunction in subjects with nascent metabolic syndromes leads to higher secretion of adipokines, such as IL-1, IL-6, IL-8, leptin, MCP-1, PAI-1, C-reactive protein, and serum amyloid A, by subcutaneous adipose tissue." (PMID 28182687, 2017). "We have demonstrated that selected inflammatory and anti-inflammatory markers (CRP, adiponectin, leptin, resistin, and Lp-PLA2) are involved in both pathogenesis of metabolic syndrome and pathogenesis of psoriasis." (PMID 28097156, 2016). "Dyslipidemia (abnormal cholesterol levels in blood) and inflammation of the white adipose tissue, two lipid disorders in metabolic syndrome, have been correlated to inflammatory biomarkers such as cytokines TNF-α and IL-6 and the C-reactive protein." (PMID 27635405, 2016). "Metabolic syndrome patients treated with EPA showed a significant reduction of small dense LDL and C-reactive protein compared with those with diet alone." (PMID 26084813, 2015). "We also provide the clinical utility of CRP to identify subjects with metabolic syndrome (MetS)." (PMID 26193292, 2015). "Our results that showed that CRP levels were significantly influenced by HDL, triglycerides, and IL-6 levels support a potential relationship between CRP levels and the metabolic syndrome." (PMID 26366318, 2015). "Plasma levels of CRP, MDA and ADMA were significantly increased while NO production was profoundly decreased in the dyslipidemia group when compared to the sham group (p < 0.05)." (PMID 25934565, 2015). "Treatment with BC (100 or 300 mg/kg/day for 8 weeks) significantly suppressed increased liver weight, epididymal fat weight, C-reactive protein (CRP), total bilirubin, leptin, and insulin in rats with induced metabolic syndrome." (PMID 26504474, 2015). "CRP levels were also significantly higher in: women than in men; patients at an estimated high global cardiovascular risk than in those at an estimated low global cardiovascular risk; and those with several metabolic syndrome markers than in those with no metabolic syndrome markers." (PMID 24564178, 2014). "LDL-c was set as the dependent variable, while age, BMI, W, VFA, SFA, SBP, DBP, FPG, 2hPG, FINS, TG, HDL-c, CRP, smoking status, CVD family history and dyslipidemia family history were designated as the independent variables to be assessed in all groups." (PMID 25398089, 2014). "In this sense, epidemiological studies have demonstrated an increase in plasma levels of inflammatory markers such as CRP, IL-6 and TNF-α in patients with metabolic syndrome and also in those with clinically overt T2D." (PMID 24495560, 2014). "In this study, we further investigated the utility of combination of CRP and HMW-adiponectin for predicting metabolic syndrome." (PMID 24069195, 2013).
metabolic syndrome (continued). "CRP and HMW-adiponectin are both well-known markers for metabolic syndrome, type 2 diabetes and CVD in various ethnics including Japanese." (PMID 24069195, 2013). "In the present study, we demonstrated that there is little additive effect of combination of CRP and HMW-adiponectin or C/A ratio for predicting metabolic syndrome compared with each of them alone." (PMID 24069195, 2013). "After adjustment for age, BMI, BF%, TC, LDL, CRP, smoking status and exercise status, the 3rd and 4th FMI quartiles had significantly higher Odds ratio for metabolic syndrome than the lowest quartile in both sexes." (PMID 23819808, 2013). "Our aim was to analyze the inter-relations between each of the components of the metabolic syndrome (MetS) and four inflammatory markers, namely high sensitivity C-reactive protein (hs-CRP), the erythrocyte sedimentation rate, the concentration of fibrinogen and the white blood cell count." (PMID 20659330, 2010). "After several generations of selection and breeding, LCR rats developed numerous markers of metabolic syndrome, including, elevated LDL cholesterol, blood pressure, triglycerides, fasting glucose, insulin, C-reactive protein, and visceral adiposity." (PMID 20584300, 2010). "Adiponectin levels correlated inversely with BMI, WHR, abnormal glucose tolerance, metabolic syndrome, serum triglyceride, VLDL and CRP." (PMID 19821969, 2009). "The metabolic syndrome is a pro-inflammatory state as evidenced by increased levels of IL-6, TNF-α, and C-reactive protein (CRP), serum amyloid A, and leptin and lower level of adiponectin." (PMID 17140429, 2006). "Decreased CRP levels were reported after 16 weeks of tadalafil in hypogonadal men with metabolic syndrome, while no significant changes were observed in shorter studies or those involving participants with lower baseline inflammation." (PMID 40806281, 2025). "A multiple regression analysis was conducted after adjusting the models for various independent variables such as age, gender, HbA1c, total cholesterol, LDL-c, HDL-c, triglycerides, Hs-CRP, BMI, nitric oxide, CAD, stroke, dyslipidemia, adipokines, and cytokines." (PMID 40243674, 2025). "In our study, patients with dyslipidemia showed higher continuous CRP levels, but this difference was not significant when comparing CRP quintiles." (PMID 40004724, 2025). "After more than two years of follow-up, it was shown that MTX did not produce lower levels of IL-1β, IL-6, CRP, or components of the metabolic syndrome than the placebo." (PMID 41155215, 2025). "Numerous tests were run and came out negative, except for the slight elevation of C-reactive protein, mild dyslipidemia, and positivity for H. pylori antigen." (PMID 40426864, 2025). "A comparison of lipid profiles and inflammatory markers showed that TG, TC, LDL-C, hs-CRP, oxidized low-density lipoprotein (ox-LDL), and 8-epi-prostaglandin F2α (8-epi-PGF2α) were all significantly higher in the dyslipidemia group, while HDL-C was slightly lower (p = 0.033)." (PMID 39859220, 2025). "Serum CRP and vitamin D levels were not significant predictors of metabolic syndrome classes in the present study, except for serum CRP for HTN class in women." (PMID 40093747, 2025). "In addition, a normalization in high BP (n = 10), IR (n = 8), Dyslipidemia (n = 10), high CRP (n = 4), high ALT (n = 7), and a remission in metabolic syndrome (n = 6) was observed (p < 0.05)." (PMID 40688482, 2025). "Metabolic syndrome (MetS), characterized by a cluster of metabolic dysregulations, such as abdominal obesity, hypertension, hyperglycemia, and dyslipidemia, leads to systemic low-grade inflammation primarily through the increased production of proinflammatory cytokines, such as IL-6, CRP, and TNF-α." (PMID 39452916, 2024). "The study subjects were divided into four groups: Normal CRP levels and non-dyslipidemia, Elevated CRP levels and non-dyslipidemia, Normal CRP levels and dyslipidemia, Elevated CRP levels, and dyslipidemia." (PMID 39247228, 2024).
metabolic syndrome (continued). "Genetic factors include: dyslipidemia, increased LDL/VLDL levels, decreased HDL, increased blood pressure, increased homocysteine levels, diabetes and obesity, systemic inflammation (elevated CRP), metabolic syndrome with insulin resistance, male gender." (PMID 38495942, 2024). "Both studies found no notable changes in CRP levels after a 12-week WB-EMS regimen in individuals with metabolic syndrome who were obese and in advanced cancer patients." (PMID 38399518, 2024). "Although the close relationships of metabolic syndrome and dyslipidemia to inflammation are well-known, the present study did not evaluate inflammatory biomarkers such as C-reactive protein." (PMID 39064767, 2024). "The correlation between ferritin levels and metabolic syndrome was stronger in studies corrected for CRP [OR = 1.90 (95% CI: 1.41–2.56; I2 = 82.4%)] versus studies not corrected for CRP [OR = 1.63 (95% CI: 1.47–1.81; I2 = 24.8%)]." (PMID 39410926, 2024). "A study conducted in Cuba reported that individuals with metabolic syndrome had hs-CRP levels four-fold higher than those without metabolic syndrome." (PMID 38542799, 2024). "Therefore, compared to CRP, EAT exhibits superior potential in predicting the occurrence of metabolic syndrome and other comorbidities in COPD patients, thereby facilitating an enhanced patient prognosis." (PMID 37400821, 2023). "Alistipes shahii was positively correlated with increased abdominal circumference, dyslipidemia (TG levels), IR, and inflammation (CRP), and it also showed a negative correlation with LDL and HDL levels." (PMID 37342535, 2023). "A CB1R blocker also reduced the C-reactive protein (CRP) levels during a 1-year treatment in overweight or obese patients with dyslipidemia, independent of statin treatment." (PMID 37371762, 2023). "Besides, a higher proportion of dyslipidemia and STEMI and higher levels of FPG, hemoglobin, eGFR, hs-CRP, peak cTnI, triglyceride, TC, and LDL-C were observed in this group." (PMID 36944934, 2023). "Moreover, the hormone concentrations in the human inflammatory fluids interdepend on the concentrations of tumour necrosis factor α (TNFα), interleukin 6 (IL6), and C-reactive protein (CRP), which are the main metabolic syndrome-related factors." (PMID 35055130, 2022). "It is important to note that none of the components of the metabolic syndrome including fasting glucose, HDL, triglyceride, waist circumference or systolic blood pressure were associated with the risk genotype or elevated CRP levels." (PMID 36313440, 2022). "In obese children without metabolic syndrome components, chemerin levels also positively correlated with the inflammatory parameter, CRP." (PMID 35327393, 2022). "The results have suggested that GXNT could regulate dyslipidemia, improve heart function, and inhibit the levels of ox-LDL, CRP, TNF-α, IL-1β, SOD, MDA, vWF, and ET-1, as well as platelet aggregation." (PMID 35935588, 2022). "Similar results were obtained for dyslipidemia for all body size phenotypes (all P < 0.05) except TC (no significance was observed for high SF after adjusting for age, sex, hs-CRP, and HOMA-IR in the MANW group) (p = 0.076)." (PMID 33659229, 2021). "Interestingly, the prevalence of metabolic syndrome and IL6, a more robust marker of low-grade, chronic inflammation was also higher in the presence of hs-CRP levels ≥3 mg/l." (PMID 32514365, 2020). "This study also found that the level of h-CRP was higher in participants with dyslipidemia than in those without dyslipidemia." (PMID 32799877, 2020). "In this study we report complementary results on CRP from the Melanesian population of Kitava, Trobriand Islands, Papua New Guinea, among whom we have previously reported an apparent absence of metabolic syndrome, type 2 diabetes and cardiovascular disease." (PMID 33334321, 2020). "At present, the relationship between CRP and components of metabolic syndrome in children has not been clearly established." (PMID 33081030, 2020).
metabolic syndrome (continued). "Indeed, elevated pro-inflammatory cytokines such as C-reactive protein (CRP), interleukin (IL)-6, including lipid peroxidation makers, such as malondialdehyde (MDA) levels, have been identified in patients with dyslipidemia." (PMID 32375340, 2020). "In model 1 (adjusted for age and sex), model 2 (additionally adjusted for disease status, including dyslipidemia, stroke, CVD, CKD, and DM), and model 3 (additionally adjusted for hs-CRP), SUA and sodium excretion remained significant predictors of prehypertension." (PMID 32460763, 2020). "Contrary to these findings, the inflammation marker hs-CRP did not increase significantly and remained largely unchanged during the study, despite increase in other variables related to the metabolic syndrome." (PMID 30935397, 2019). "Tested transcripts did not correlate with gender, age, diabetic nephropathy, types of dyslipidemia, active HBV/HCV infection, liver enzyme activities but ALP with RXRA transcript, inflammatory state assessed by plasma C-reactive protein, or lipid-modifying treatment." (PMID 31775661, 2019). "An inverse correlation between ALT and skeletal muscle mass index as well as total body fat and additionally negative correlations with CRP, components of metabolic syndrome, and LDL-cholesterol were reported." (PMID 31534560, 2019). "Hence, many studies to date have shown higher high-sensitive C-reactive protein (hs-CRP) levels, reflecting inflammation among patients with metabolic syndrome." (PMID 30862094, 2019). "CRP was significantly higher in the group with metabolic syndrome, irrespective of the women’s genotypes." (PMID 30383538, 2018). "In contrast, FVC% of predicted was significantly associated with ADPN, measures of adiposity, metabolic syndrome, OSA and CRP, but not with smoking." (PMID 29609563, 2018). "Thus, the objective of the study was to determine the association of dietary patterns, anthropometric measurements, and metabolic parameters with inflammatory markers using CRP and NLR among middle-aged and older adults with metabolic syndrome in Taiwan." (PMID 30454030, 2018). "Multivariate logistic regression was performed to evaluate the association of dietary patterns, anthropometric measurements, and metabolic parameters with C-reactive protein (CRP) and neutrophil-to-lymphocyte ratio (NLR) in men and women with metabolic syndrome." (PMID 30454030, 2018). "We assessed the association between ADPN and lung function by multivariate linear regression analyses and adjusted for age, gender, height, smoking habits, weight, body mass index, waist-hip ratio, metabolic syndrome, obstructive sleep apnoea (OSA) and C-reactive protein." (PMID 29609563, 2018). "The associations did not materially change after adjusting for waist circumference (data not shown) or excluding individuals with a CRP level ≥0.3 mg/dL (data not shown) or those with a history of dyslipidemia (data not shown)." (PMID 28552966, 2017). "However, adjusting for the CRP level in the present study did not change the association between serum ferritin and lipid parameters, suggesting that low-grade inflammation may not explain the association between serum ferritin levels and dyslipidemia." (PMID 29272309, 2017). "In the current study, we tested the effects of metformin on inflammation, oxidative and dicarbonyl stress in an animal model of inflammation and metabolic syndrome, using spontaneously hypertensive rats that transgenically express human C-reactive protein (SHR-CRP)." (PMID 26963617, 2016). "The selected variables were age, female sex, CRP value, absence of dyslipidemia, and poorly differentiated tumor." (PMID 27082598, 2016). "For example, in the WOSCOP study, patients with the metabolic syndrome and elevated CRP had increased cardiovascular mortality (RR 2.75 (95% CI, 2.1-3.6)) compared to patients without the metabolic syndrome and with low CRP values." (PMID 25163828, 2014).
metabolic syndrome (continued). "Although our results demonstrate that plasma PTX3 levels associate inversely with components of metabolic syndrome, the study does not support a relation between this pentraxin and recurrent CHD risk, unlike other pentraxin family members such as CRP." (PMID 24705587, 2014). "Recently, we derived a new strain of “humanized” spontaneously hypertensive rats (SHR-CRP) in which transgenic expression of human C-reactive protein (CRP) in liver induces inflammation, oxidative stress, several features of metabolic syndrome, and target organ damage." (PMID 25010431, 2014). "Additionally, nitric oxide (NO) production was reduced and serum levels of malondialdehyde (MDA), C-reactive protein (CRP) and asymmetric dimethylarginine (ADMA) were profoundly elevated in dyslipidemia group." (PMID 25361814, 2014). "Among subjects with lacunar subtype and metabolic syndrome, PWV (after correction for age and gender) was more significantly and positively related to CRP, IL-1β, IL-6, TNF-α, vWF and PAI-1 compared to subjects without metabolic syndrome and the same subtype of stroke." (PMID 24571954, 2014). "Additionally, NO production was profoundly declined in accompany with elevation of CRP, sVCAM, sICAM and MDA in the dyslipidemia groups (p < 0.05)." (PMID 25491404, 2014). "The BMI, CRP, serum uric acid, and serum total bilirubin concentration were statistically significantly higher among those with metabolic syndrome than among those without the syndrome (p<0.001 for all factors)." (PMID 25299452, 2014). "Both dietary fat intake and body fat % were associated with higher levels of peripheral indices related to metabolic syndrome, including total and LDL blood cholesterol, plasma C-reactive protein, blood pressure, and WHR, as indicated by significant positive correlations." (PMID 24376410, 2013). "Finally we evaluated additive effects of CRP and HMW-adiponectin on BMI and waist circumference for prediction of metabolic syndrome." (PMID 24069195, 2013). "Therefore, in this longitudinal cohort study we sought to address the following questions: 1) Is there any additive effect of the combination of CRP and HMW-adiponectin for prediction of metabolic syndrome compared with each of them alone?" (PMID 24069195, 2013). "For example, C-reactive protein and haptoglobin, which both increased with age in the ASD subjects, are components of the acute phase response, although these same proteins have also been used as biomarkers for immune disorders and metabolic syndrome." (PMID 23915542, 2013). "The aim of this study is to investigate the prevalence of metabolic syndrome (MetS), carotid intima media thickness (IMT), and serum C-reactive protein (CRP) levels in patients with chronic obstructive pulmonary disease (COPD), and the possible relationships among them." (PMID 24040911, 2013). "Further studies are needed to clarify whether the combination of CRP and HMW-adiponectin improve predictive ability for development of metabolic syndrome and type 2 diabetes." (PMID 24069195, 2013). "A total of 750 subjects (558 men and 192 women, age 46±8 years) who had not met the criteria of metabolic syndrome and whose CRP and HMW-adiponectin levels had been measured in 2007 were enrolled in this study." (PMID 24069195, 2013). "Whereas increased metabolic syndrome incidence was observed in males with elevated leptin regardless of CRP levels, females with elevated CRP or leptin had increased incidence of metabolic syndrome." (PMID 22533665, 2012). "In the current study, CRP and IL-6 levels measured three years later in the same cohort were also higher in patients with metabolic syndrome but did not pass cutoffs for statistical significance (p<0.08 for CRP and p<0.13 for IL-6)." (PMID 22701684, 2012). "After 12 weeks of exercise, both of the obese children groups, with and without metabolic syndrome, showed reduced body weight, body mass index (BMI), and CRP level, and increased HDL-C level." (PMID 22691465, 2012).